ATM (ATM serine/threonine kinase)
Diseases named in the same sentence as ATM in open-access papers (continued):
Sharing a sentence is not in itself a finding about the gene and the disease.
tumor (continued). "The relative efficacy of AZD7648 75 mg/kg BID alone (blue) and in combination (orange and purple) delivered by the Microformulator to FaDu ATM KO cells was similar to that seen in the in vivo FaDu ATM KO tumour xenograft model." (PMID 35617197, 2022). "Estimated common deletion regions (CDRs) were observed in many tumor suppressor genes, such as ATM, CDKN2A, FAT1, miR31HG, PTEN, and RB1, in the SNP array-based COSMIC datasets." (PMID 36531022, 2022). "Survival experiments performed over a longer time period showed that combining ATM inhibition with immunotherapy increased the overall survival compared with single treatments alone in both tumor models." (PMID 36353752, 2022). "Combined HMGB1 and p-ATM, the results showed patients with both positive expression of HMGB1 and p-ATM have larger tumor and more distant metastasis than those with single positive/double negative expression of HMGB1 and p-ATM." (PMID 36260180, 2022). "First, the therapeutic scope of PARP inhibitors is expanding to other tumor types, most with BRCA or ATM mutations, such as endometrial, urothelial, SCLC, STS, mesothelioma, and gastric cancer." (PMID 36254250, 2022). "Meanwhile, we observed that ATM is activated by TMZ in both resistant and sensitive tumor cells, and XAF1 induction causes further activation of ATM, which is required for TMZ-induced apoptosis." (PMID 35274103, 2022). "For instance, although we employed multiple techniques to study the abundance of ATM in all tumor samples, the paucity of available material prevented us from applying all the techniques to each sample." (PMID 36555667, 2022). "Our current studies clearly demonstrated that both SCT and CA can initiate ATM‐associated DDR in various types of tumor cells, resulting in tumor cell senescence." (PMID 34747157, 2022). "Non-malignant cells possess a functional G1-checkpoint, in contrast to most NSCLC cells, it is proposed that selective tumor radiosensitization can be achieved by abrogation of the G2-checkpoint using inhibitors of ATM or ATR." (PMID 34198619, 2021). "Here, we compare the effects of α-radiation from Ra-223 or X-ray radiation upon combination with the DNA-PK inhibitor M381417 and the ATM inhibitor AZD-139018 in several cell lines (tumor cell lines, normal cell lines and one immortalized cell line)." (PMID 34853427, 2021). "Thus, the mutational status of genes such as ATM may be one of several factors that, in the setting of a multidisciplinary BrM tumor board, could guide whether to approach a BrM with primary SRS, with surgery, or to reimage the brain following a trial of systemic therapy." (PMID 35145903, 2021). "Regarding the molecular mechanism, we found that ALDOA inhibited the DDR and improved activation of the cell cycle checkpoint PLK1 by suppressing ATM, which promotes tumour cell progression." (PMID 34565365, 2021). "Using a molecular biology approach, we identified a novel mechanism by which the phosphorylation of PTEN by ATM regulates its cellular redistribution and contributes to the tumor suppressor function of the protein." (PMID 34059798, 2021). "Previous studies have also demonstrated that ATR inhibitors exhibit strong antitumor activity against HRR-deficient tumor models, such as those that are deficient in BRCA1/2, RAD51, or ATM-mutated." (PMID 34552099, 2021). "ATM gene produces a protein kinase playing important role in triggeringproper cellular response to DNA damage and similar to the other tumor suppressor genes,promoter methylation is the main epigenetic mechanism which can prevent ATMtranscription." (PMID 34308577, 2021). "Specifically, our results suggest that after exposure of G1- or G0-phase cells to low IR doses, the activation of the G1 checkpoint is exclusively mediated by ATM both in normal 82-6 hTert cells, as well as in the tumor cell line, A549." (PMID 35011623, 2021).
tumor (continued). "ATM signaling is known to induce tumor progression in a nuclear factor kappa B-dependent manner that promotes EMT." (PMID 34638295, 2021). "Further, we found emerging of new JAK2 and ATM alterations in patient B8 at the second time point, indicating possible evolving tumor clonal growth during disease progression." (PMID 34336686, 2021). "We characterized the kinase-signaling network, where we identified LCK and EGFR as interconnected, down-regulated kinases and the tumor suppressors ATM and CDK2 as interconnected, up-regulated kinases." (PMID 34238254, 2021). "The most frequent top mutated genes in tumor fragments of women were USH2A, ATM, IGF2R, MKI67, and MAP3K1 (median variants per sample = 20; missense, nonsense, and splice site mutations)." (PMID 34680380, 2021). "For this purpose, we evaluated the necessity of ATM for anti-tumor effects with a combination of cisplatin and 5-AZA using an in vivo mouse model." (PMID 34503060, 2021). "For example, the pattern of somatic mutations in ataxia telangiectasia mutated (ATM) shows signals of positive selection across 11 and 5 tumor types in TCGA and ICGC cohorts, respectively." (PMID 33179738, 2021). "By using two different cell systems, we were able to dissect the molecular mechanism responsible for the in vivo phenotype and reveal a novel regulatory function of ATM, one of the main tumor suppressors in cells." (PMID 34059798, 2021). "ATM inhibition (via small molecule or short-hairpin RNA) enhanced anti-tumor immunity in combination with ICI and radiation in murine models of ovarian and pancreatic cancers." (PMID 34298632, 2021). "Gene alterations in BRCA1, BRCA2, and ATM were detected in 2.0, 10.7, and 8.8%, respectively, of cfDNA samples and in 1.6, 8.2, and 5.8%, respectively, of tumour tissue samples." (PMID 33630412, 2021). "In this regard, we evaluated patient tumor specimens for the presence of ATM mutations via targeted next-generation sequencing (NGS) and for loss or reduction of ATM protein expression via immunohistochemistry (IHC)." (PMID 34552099, 2021). "In T-PLL, tumor cells have a dysfunctional ATM which works as a DNA repair gene sensitizing tumor cells to DNA damage agents." (PMID 33728186, 2021). "At first sight, this is an unexpected result since ATM/ATR inhibitors are generally thought to sensitize tumor cells to genotoxic agents." (PMID 33808326, 2021). "SL is built around the idea that mutations, in this example, genes involved with HRR, such as BRCA and ATM, are advantageous to the tumor cell." (PMID 34712892, 2021). "The ATM and CHEK2 genes encode proteins that act as tumor suppressors and are involved in the DNA damage response following generation of DNA double-strand breaks (DSBs)." (PMID 33919281, 2021). "The negative regulation of HK2 by ATM was also shown by ursolic acid promoting the apoptosis of tumor cells by inhibiting HK2-mediated glycolysis, but activating ATM35." (PMID 34652890, 2021).
tumor (continued). "The results remind us the correlation between VM formation and tumor grade and recurrence, suggesting a probable link between VM formation and ATM/ATR activation." (PMID 34483751, 2021). "Descriptive genomic analysis of pre-NAC tumor samples identified mutations in ERBB2 and DNA repair genes; ATM, RB1, FANCC, and ERCC2 were associated with tumor response to NAC." (PMID 33799514, 2021). "Another report assessed the promoter methylation status of ATM among Indian breast cancer cases which showed significant higher ratio of promoter hyper methylation in tumor tissues compared with normal samples." (PMID 33883026, 2021). "In preclinical studies, inhibition of ATM during radiotherapy enhanced tumor immunogenicity and tumor sensitivity to PD-L1 immune checkpoint blockade." (PMID 34337349, 2021). "Given the discordance between BrM and primary tumor genotype, sampling of the BrM ATM genotype would be expected to provide the most robust biomarker for radiosensitivity." (PMID 35145903, 2021). "Tumor cells with mutation in BRCA1 or BRCA2 genes exhibit defective HR (referred to as BRCAness phenotype) and are pronounceably hypersensitive to ATM and PARP inhibition." (PMID 34718714, 2021). "Activation of this ATM/TAK1/PrPC pathway mediates tumor cell radioresistance and is a known regulator of CSC functions." (PMID 34638302, 2021). "Of note, ATM is often considered a major tumor suppressor because of its ability to induce apoptosis and cell cycle arrest." (PMID 34070860, 2021). "Analogously, ATM inhibition induces tumor growth delay and overcomes tumor resistance to anti–PD-1 therapy." (PMID 34970273, 2021). "Our results highlight a concern for the use of immunohistochemistry (IHC) to assess ATM levels with the expectation that patients whose tumor has low ATM would respond to ATRi." (PMID 33782497, 2021). "In mice models, low doses of niraparib and irinotecan were effective and synergistic in ATM-mutated HCT116 xenograft, in which they induced complete tumor regressions in 60% of treated mice." (PMID 33407715, 2021). "In particular, a study using genetically modified mouse models showed that mice developing Kras-driven pancreatic cancer showed more aggressive tumor growth in the case of conditional deletion of ATM." (PMID 34638302, 2021). "These ATM-induced epigenetic modifications are associated with activating the CSC gene expression, enriching CSC populations, and promoting tumor formation and growth in mouse xenograft models." (PMID 34638302, 2021). "Other genes that were subject to subclonal involvement, suggesting late alterations in tumor progression, included ATM and 22q arm(deletion)." (PMID 34504292, 2021). "The most frequently mutated genes in the tumor fragments of women were USH2A, ATM, and IGF2R; in female dogs, they were USH2A, BRCA2, and RRM2." (PMID 34680380, 2021). "For example, ATM is highly expressed in the microvascular proliferative zones of the tumor, EGFR is highly expressed in the cellular bulk of the tumor while MET is enriched in the leading edges and the necrotic tumor regions." (PMID 33765907, 2021). "Taken together, these results suggested that late NDV infection and syncytium formation triggered by virulent F-HN co-transfection significantly activated the ATM-mediated DSB signaling pathway in tumor cells." (PMID 32479542, 2020). "In conclusion, in this study, we demonstrated the role of ATM inhibition on tumor growth in gemcitabine-resistant and DNA polymerase θ-deficient BTC cells." (PMID 33182492, 2020). "Here, we provide several possible explanations why late NDV infection significantly provoked the ATM-dependent DSB signaling pathway in tumor cells to facilitate progeny replication." (PMID 32479542, 2020).
tumor (continued). "This suggests that Tdp2−/−Atm−/− tumours likely reflect direct functions of ATM in the repair of TOP2-induced DSBs, and not only in their signalling for checkpoint and apoptosis." (PMID 32060399, 2020). "Through further analysis, we found that ATM is likely to impact the efficacy of ICIs by affecting the tumor immune microenvironment." (PMID 32922441, 2020). "ATM is a well‐recognized tumor suppressing gene located on chromosome 11q 22‐23, in the family of PIKK genes and is activated with double DNA strand breaks." (PMID 33098265, 2020). "This regimen induced growth delay in the ATM-WT and tumour regression in the ATM-KO tumours, thus demonstrating proof of principle that low-dose gemcitabine can be used as a sensitiser to AZD6738 in vivo." (PMID 32741974, 2020). "Surprisingly, it was also detected with lower intensity in all F10 tumor foci with bi-allelic ATM inactivation, suggesting compensation by a related kinase." (PMID 32680567, 2020). "This stratified tumours according to T cell activation, NK‐cell activation, complement cascade, ATM, Rb, angiogenic, MAPK, ECM receptor and histone modification signalling." (PMID 31730267, 2020). "γH2AX positivity was higher in the ATM-KO tumours following ATRi/gem treatment compared to the ATM-WT (p < 0.05)." (PMID 32741974, 2020). "They further demonstrated the same effect in a xenograft tumor model and suggested inefficient DNA repair, possibly due to impaired activation of ATM and DNAPKcs upon dactolisib treatment." (PMID 32903756, 2020). "We first found that 50 mg/kg AZD6738 monotherapy, once daily for 5 consecutive days a week, induced significant growth delay in the ATM-null tumours." (PMID 32741974, 2020). "Meanwhile, we observed that both velogenic (Herts/33) and lentogenic (La Sota) strains activated the ATM-mediated DSBs in A549 tumor cells." (PMID 32479542, 2020). "In this study, oncolytic NDV infection significantly up-regulated the phosphorylation of ATM, H2A.X, and Chk2 in tumor cells, suggesting that NDV infection indeed altered the phosphorylation of PTM signals." (PMID 32479542, 2020). "The ATM PVs harbored by all three BBC patients were mainly observed in the luminal B tumor phenotype." (PMID 32854451, 2020). "The methylation status of five tumor-suppressor gene promoters was assessed: ATM including four evaluated CpG sites (CpG 1–4), PITX2 (CpG 1–5), RASSF1 (CpG 1–3), PTEN (CpG 1–6), and TIMP3 (CpG 1–6)." (PMID 33375383, 2020). "Recent studies indicate that these DNA double stand breaks and ensuing activation of DNA damage response factors such as ATM play important but previously underappreciated roles in carcinogenesis and tumor growth." (PMID 32566127, 2020). "Taken together, these themes support the interpretation that selection against Mre11 complex-dependent ATM signaling occurs during tumor progression, and that Rad50-dependent ATP metabolism is crucial for ATM activation by the Mre11 complex." (PMID 32187176, 2020). "In all scenarios, the combination of the HDAC and ATM inhibitor produced a significant increase in the tumor cell killing when compared to the untreated or single agent treated cells." (PMID 32973968, 2020). "In summary, the activation of MRN was essential for sensing and signaling ATM-mediated DSBs in tumor cells, which, in turn, was necessary for membrane fusion and oncolytic NDV replication in tumor cells." (PMID 32479542, 2020).
tumor (continued). "In this analysis, ATM and ATR were found to be associated with higher mutational burden (i.e., 50 mutations/tumor) in all samples except one." (PMID 32300177, 2020). "Baseline tumor specimens were available for NGS testing from 32 patients (1 with pathogenic ATM mutation) and ATM IHC testing from 30 patients (2 with 100% ATM IHC loss)." (PMID 32568634, 2020). "It has been suggested that this is probably due to a deficiency in HRR associated genes ATM, MRE11A, H2AFX, and CHEK1; such tumours very rarely have concurrent MYCN amplification." (PMID 32577161, 2020). "To support these findings, we tried to measure the amounts of acetyl-CoA in tumor tissues and detect the levels of p-ATM and SOX2." (PMID 32641713, 2020). "Previous studies on curcumin (CUR) tumor suppression function show that inhibition of ATM production completely reverses CUR-induced cell cycle arrest and anti-angiogenesis." (PMID 32518522, 2020). "The mutation allele frequencies of ATM and JAK3 were significantly correlated with the disease stage, and mutated KMT2D, ASXL3 and JAK3 were positively correlated with the metabolic tumor burden of the patients." (PMID 32695399, 2020). "ATM is thought to regulate the chromosomal instability as well as promote anti-tumor effect by inducing DNA damage and killing of tumor cells." (PMID 33329696, 2020). "The Tumor Sequencing Project, investigating 188 LAD cases, also found that ATM was one of the most common genes that somatically mutated in LAD26." (PMID 32393777, 2020). "ATM is a tumor suppressor gene that is inactivated in 2–8% of common epithelial cancers, including breast and pancreatic." (PMID 32015826, 2020). "Taken together, our results suggest that TP5 acts synergistically with TMZ and IR by reducing the ability of tumor cells to repair DNA-damage caused by TMZ or IR, through the inhibition of ATM phosphorylation." (PMID 32708903, 2020). "Next-generation sequencing (NGS) of genetic aberrations and ATM immunohistochemistry (IHC) were conducted on archival and/or fresh tumor specimens, when available, to assess predictive markers of response." (PMID 32568634, 2020). "LOH or AST mutation was detected in at least one tumor with PALB2, ATM, RAD51D, BARD1, BRIP1, RAD51C, or NF1 germline mutation." (PMID 32566746, 2020). "We found that late NDV infection and membrane fusion activated the ATM-Chk2 axis in tumor cells, which expands prior understanding of the membrane fusion process and NDV infection." (PMID 32479542, 2020). "Using gene expression profiling, it would be possible to identify patient tumours with PTEN mutations, suitable for treatment with ATM inhibitors as a neo-adjuvant or adjuvant with radiotherapy." (PMID 33396656, 2020). "This patient had six verified tumor mutations (ARID1B, ATM, CDK8, FANCA, and two RASA1 mutations), all of which were detected in the preoperative plasma sample." (PMID 30554450, 2019). "We have recently shown that adoption of a hyperfractionated irradiation scheme increases the radiosensitizing capacity of ATM inhibitors towards the COMI GIC-driven orthotopic tumor model." (PMID 30961616, 2019). "ATM signalling pathway alterations and the presence of a COSMIC Signature 3 implied the majority of tumours contained some form of homologous repair deficiency." (PMID 30763338, 2019).